FOXP3 (forkhead box P3)
Diseases named in the same sentence as FOXP3 in open-access papers (continued):
Sharing a sentence is not in itself a finding about the gene and the disease.
systemic sclerosis (20 papers, 2012 to 2025). A chronic disorder, possibly autoimmune, marked by excessive production of collagen which results in hardening and thickening of body tissues. "Polymorphisms in FOXP3, the major Treg transcription factor, are associated with the incidence of systemic sclerosis, highlighting the intricate link between these cells and disease pathogenesis." (PMID 39170360, 2024). "In early systemic sclerosis (SSc), inflammatory cells, including IL-17+ and Foxp3+ lymphocytes, infiltrate the skin." (PMID 41009491, 2025). "Tregs play a pivotal role in the pathogenesis of systemic sclerosis, characterized by FOXP3 expression and the production of TGF-β, a potent mediator of tissue fibrosis." (PMID 39170360, 2024). "CD4+ cells from patients with systemic sclerosis subjected to ATRA were more abundant in Foxp3 at the mRNA and protein level." (PMID 34281195, 2021). "In adults with systemic sclerosis, and a peanut allergy, FOXP3 hypermethylation seems to play also an important mechanistic role." (PMID 32210181, 2020). "in CD4+ T cells from patients with systemic sclerosis, treatment with all-trans retinoic acid, a natural derivative of vitamin A, increases the expression of FOXP3 and, subsequently the proportion of Treg cells by promoting demethylation of the FOXP3 promoter." (PMID 38510251, 2024). "ATRA treatment of systemic sclerosis (SSc) CD4+ T cells induces Foxp3 expression with enhanced immunosuppressive functionality." (PMID 34239942, 2021). "It was reported that differences in CD4+CD25+Foxp3+ and CD4+CD25+CD127- iTreg frequencies exist in the blood of patients with systemic scleroderma." (PMID 22905732, 2012). "In systemic sclerosis (SSc) patients, while the proportion of Foxp3+ skin Tregs was not changed between SSc vs. healthy individuals, the Th2 cytokine production in skin SSc Tregs was significantly increased as compared to skin Tregs isolated from healthy individuals." (PMID 37197653, 2023). "It has also been shown that, in blood samples from normal healthy donors and patients with systemic scleroderma, about 35 % of CD127low/− cells that did not express Foxp3 and, conversely, about 30 % of CD127+ cells expressed Foxp3." (PMID 27156107, 2016).
vitiligo (20 papers, 2014 to 2025). Generalized well circumscribed patches of leukoderma that are generally distributed over symmetric body locations and is due to autoimmune destruction of melanocytes. "The FOXP3 gene located on the X chromosome was also a risk factor for vitiligo in several ethnicities." (PMID 35643735, 2022). "The IKZF4 gene, associated with vitiligo in European and Chinese individuals, exerts a FOXP3-mediated gene silencing on T regulatory cells (Tregs)." (PMID 35643735, 2022). "No further studies are available on FOXP3 gene polymorphisms in relation to vitiligo, however, in psoriatic patients, one of the upstream SNPs of FOXP3 gene rs3761548 was found significant association with the disease." (PMID 26257775, 2015). "Therefore, to clarify the role of Tregs in vitiligo pathogenesis, we aimed to study Tregs' frequency, suppressive capacity, and associated suppressive molecules (FOXP3, IL-10, and TGF-β) in vitiligo patients through meta-analysis approach." (PMID 36164321, 2022). "Overall, a significant increase in CD4 + and CD8 + T cells, along with a marked reduction in Forkhead box P3 (Foxp3)-expressing Tregs, was observed in the marginal skin of both stable and active vitiligo cases." (PMID 40703229, 2025). "This study further demonstrates the significant upregulation of miRNA-146a and proinflammatory mediators (NF-κB, IL-6, and TNF-α), accompanied by the downregulation of Foxp3 in vitiligo tissues." (PMID 40723924, 2025). "In summary, the present integrative analysis highlights the central roles of CUL3, NRF2, miRNA-146a, and Foxp3 in the pathogenesis of vitiligo, linking oxidative stress and immune dysregulation to melanocyte loss." (PMID 40723924, 2025). "In this study, the authors aim to comprehensively profile the expression of CUL3 and key regulatory molecules, including NRF2, NF-κB, miRNA-146a, and Foxp3, in patients with vitiligo, integrating clinical, in silico docking, and bioinformatics analyses." (PMID 40723924, 2025). "The reduction of proteins such as FOXP3 has been proven to be closely related to the progression of vitiligo." (PMID 40703229, 2025). "The marked downregulation of Foxp3 observed in our study is in agreement with prior reports of reduced Treg function in vitiligo." (PMID 40723924, 2025). "Meanwhile, we observed a significant increase in the number of CD4+Foxp3+ Tregs in the peripheral blood of vitiligo mice treated with 2D‐Exos and 3D‐Exos compared to the PBS group, higher in 3D‐Exos treatment group." (PMID 38887870, 2024). "Our meta-analysis suggested significantly decreased FOXP3 expression levels in blood and skin of vitiligo patients." (PMID 36164321, 2022). "Our meta-analysis suggested a significant decrease in FOXP3 levels in vitiligo patients when compared to controls (p < 0.00001)." (PMID 36164321, 2022). "As FOXP3 is an indispensable molecule for Tregs' number and suppressive function, next we assessed FOXP3 expression levels in blood and skin of vitiligo patients." (PMID 36164321, 2022). "A total of 8 studies comprised of 76 vitiligo patients (human studies) and 21 vitiligo mice (animal studies) studied the FOXP3 protein expression pre- and posttreatment." (PMID 36164321, 2022). "Since FOXP3 plays a crucial role in phenotype and suppressive function of Tregs, our recent study also reported a positive correlation of FOXP3 levels with Treg cells' suppressive capacity in vitiligo." (PMID 36164321, 2022). "Previously, a total of four studies comprised of 179 vitiligo patients and 105 controls carried out disease activity-based analysis for FOXP3 expression." (PMID 36164321, 2022). "The pooled results of the meta-analysis suggested for crucial role of decreased Treg cells' frequency and FOXP3 expression in vitiligo pathogenesis and progression." (PMID 36164321, 2022).
vitiligo (continued). "Candidate gene studies highlight the role of autoimmunity in vitiligo, as polymorphisms in IL1B, IL4, PSMB8, NLRP1, NPY, FOXP3, and IFNG genes were found to be associated with vitiligo." (PMID 36164321, 2022). "The disease activity-based analysis suggested for reduced Tregs' frequency and FOXP3 expression in active vitiligo patients (p = 0.05 and p = 0.01)." (PMID 36164321, 2022). "Genome-wide association studies (GWAS) have identified more than 50 genetic risk variants for vitiligo, including genes related to cytolysis (GZMB, CTLA4, FOXP3) and melanocyte function (TYR, MC1R, XBP1)." (PMID 36182982, 2022). "After the initial screening, we found that a total of 14 studies, comprised of 831 vitiligo patients and 755 controls, assessed the FOXP3 levels in vitiligo." (PMID 36164321, 2022). "Regulatory T cells (Tregs) play a key role in maintaining peripheral tolerance; however, Tregs' number, suppressive function, and associated suppressive molecules (FOXP3, IL-10, and TGF-β) are found to be reduced in vitiligo patients." (PMID 36164321, 2022). "FoxP3 expression in serum and lesional skin, FoxP3 mRNA expression in lesional and perilesional skin declined in vitiligo patients." (PMID 33200838, 2021). "Preclinical studies have provided promising results when using polyclonal CD4+CD25+FoxP3+ Tregs to enforce immune tolerance in various mouse models, including vitiligo." (PMID 33335528, 2020). "We examined the T-cell-associated transcription factors FOXP3 and TBX21 (Tbet), which are the master regulators in Tregs and Th1/Tc1 cells respectively, and found they were induced in VKH and vitiligo compared to controls." (PMID 33384688, 2020). "Flow cytometric analysis revealed a significant decrease in the percentage of CD4+Foxp3+HO‐1+ T cells in vitiligo patients." (PMID 29974998, 2018). "In the present study the percentage of peripheral FoxP3+ cells in vitiligo patients was also significantly low compared to healthy controls and this matches previous reports." (PMID 26788051, 2015). "The GG genotype of rs2232365 decreases the FOXP3 expression and affects Treg cell function, thus disrupt the Th1/Th2 balance, leading to the pro-inflammatory disease vitiligo." (PMID 26257775, 2015). "Additionally, FOXP3 was markedly decreased in both the blood and skin tissues of patients with vitiligo." (PMID 40703229, 2025). "Interestingly, while a significant effect of age relative to vitiligo onset on Foxp3 expression was detected in growing feathers of Smyth chickens (P = 0.0015), no significant increases were observed relative to -39d." (PMID 38720888, 2024). "Therefore, the decreased expression of FOXP3 in lesional skin, as suggested by our meta-analysis, further establishes the role of impaired Tregs' suppressive capacity in vitiligo pathogenesis." (PMID 36164321, 2022). "Additionally, our meta-analysis suggested the role of decreased FOXP3 expression in disease activity of vitiligo." (PMID 36164321, 2022). "Moreover, FOXP3, a key Tregs' transcription factor, was significantly reduced in blood and skin of vitiligo patients (p < 0.00001)." (PMID 36164321, 2022). "Interestingly, our recent study has also suggested that the decreased expression of FOXP3 leads to impaired Tregs' suppressive capacity in vitiligo." (PMID 36164321, 2022). "Further, we carried out disease activity-based analysis for FOXP3 expression in vitiligo." (PMID 36164321, 2022). "A statistically significant negative correlation was observed between the percentage of CD4+CD25+ T cells and FoxP3+ Tregs in the peripheral blood of vitiligo patients and vitiligo disease activity according to VIDA score (r = −0.851, P < 0.001 and r = −0.512, P < 0.05, resp)." (PMID 26788051, 2015).
vitiligo (continued). "The percentage of peripheral FoxP3+ Tregs in vitiligo patients group ranged from 0.6% to 2.1% of CD4+ T cells with a mean of 1.09% ± 0.96% which was significantly lower than that of control group which ranged from 0.04% to 2.0% with a mean of 1.44% ± 0.24% (P < 0.05)." (PMID 26788051, 2015). "However, the interplay between miRNA-146a and Foxp3 in vitiligo remains to be fully elucidated." (PMID 40723924, 2025). "The decreased FOXP3 protein and transcript levels in the blood may be due to the reduced Tregs' frequency in vitiligo patients; therefore, our meta-analysis further suggests for the role of decreased Tregs' frequency in vitiligo pathogenesis." (PMID 36164321, 2022). "Furthermore, we evaluated Tregs' frequency, FOXP3, and IL-10 expression posttreatment in vitiligo." (PMID 36164321, 2022). "However, FOXP3 expression has been found to be altered in vitiligo patients." (PMID 36164321, 2022). "Moreover, the interventions targeting Treg cells/FOXP3 gene networks that could suppress the immune responses may open new insights for effective therapeutic approaches for vitiligo." (PMID 26257775, 2015). "After initial screening, 913 studies were excluded as they contained duplicate records and did not involve assessment of Tregs' frequency, Tregs' suppressive capacity, FOXP3 levels, IL-10 levels, and TGF-β levels in vitiligo." (PMID 36164321, 2022). "According to the studies included in the meta-analysis, treating vitiligo mouse models with antigen-specific CAR Tregs, PD-L1 fusion peptides, and CCL22 DNA reverses depigmentation by increasing the number of Tregs and FOXP3 expression in the skin." (PMID 36164321, 2022). "Decreased percentage of peripheral CD4+CD25+ Tregs and decreased expression of FoxP3+ might impair the suppressive activity of Treg cells on cell proliferation with breakage of tolerance to melanocyte self-antigens which could contribute to the pathogenesis of vitiligo." (PMID 26788051, 2015). "In the current study, a significant positive correlation was observed between the peripheral percentage of FoxP3+ cells and that of CD4+CD25+ T cells in vitiligo patients." (PMID 26788051, 2015). ", while a statistically significant positive correlation was observed between peripheral percentage of FoxP3+ Tregs and the percentage of CD4+CD25+ cells in vitiligo patients (r = 0.369, P < 0.05)." (PMID 26788051, 2015). "Our findings of a negative correlation between Foxp3 and both disease activity and miRNA-146a further underscore the interplay between immune regulation and oxidative stress in vitiligo." (PMID 40723924, 2025). "Examination of growing feathers from vitiligo-susceptible Brown line chickens revealed anti-inflammatory immune activities which may be responsible for preventing vitiligo (IL10, CTLA4, FOXP3)." (PMID 38720888, 2024). "Therefore, we performed a meta-analysis to study Treg cells' frequency, Tregs' suppressive function, FOXP3, IL-10, and TGF-β expression in vitiligo patients." (PMID 36164321, 2022). "Skin manifestations is a common finding in IPEX but vitiligo has not yet been reported although FOXP3 gene seems to be relevant in individuals affected by vitiligo." (PMID 36503523, 2022). "Compared with healthy controls, the percentage of Tregs (CD4+Foxp3+ T cells) in the blood samples from vitiligo patients had a tendency to decrease, but with no statistical difference." (PMID 29974998, 2018). "Among the clinical parameters of our vitiligo patients, a significant negative correlation was detected between the percentage of FoxP3+ cells in peripheral blood and VIDA score." (PMID 26788051, 2015). "Each of circulating CD4+CD25+ Tregs percentage and FoxP3+ Tregs percentage did not correlate with patients' age, vitiligo disease duration, or VASI score." (PMID 26788051, 2015).
vitiligo (continued). "Moreover, the FOXP3 expression was significantly reduced in lesional skin as compared to perilesional and nonlesional skin of vitiligo patients, indicating that FOXP3 expressing Treg cells are indeed crucial for suppressing autoreactive melanocyte-specific CD8+ T cells in lesional skin." (PMID 36164321, 2022). "Interestingly, we found a significant decrease in FOXP3 levels in lesional skin when compared to perilesional skin (p = 0.007, SMD: -9.77 [-16.91, -2.62]) and nonlesional skin (p = 0.04, SMD: -1.01 [-1.95, -0.06]) in vitiligo patients." (PMID 36164321, 2022).
eosinophilia (19 papers, 2012 to 2025). "Presence of FoxP3+ Tregs during viral respiratory infections such as RSV has been shown to limit RSV-induced pathology caused by eosinophilia, CD4+ and CD8+ T cells in wildtype and FoxP3 DTR mice (allowing depletion of FoxP3+ Tregs)." (PMID 36466865, 2022). "CD4+FoxP3+ Tregs can reduce eosinophilia, impair humoral responses and secret an inhibitory cytokines, such as IL-10 and TGFβ, which suppress the effector functions of activated T cells and reduce inflammation." (PMID 33101290, 2020). "Foxp3 acts as a master switch gene for CD4+CD25+Treg cell development and function, and a mutation in Foxp3 leads to hyper-IgE, eosinophilia and dysregulated Th1 and Th2 cytokine production." (PMID 26445348, 2015). "Improvements were confirmed by reduced symptom scores, lower serum total and OVA-specific IgE levels (ELISA), decreased Th2 cytokine expression (RT-PCR), diminished mucosal eosinophilia and goblet cell hyperplasia (histology), and enhanced Foxp3 expression in nasal tissues (immunofluorescence)." (PMID 40430867, 2025). "However, the modest reduction of ex-Foxp3 Th2 cells in the absence of Il4ra-expressing T reg cells led to a significant reduction of airway eosinophils, suggesting that Il4ra-dependent ex-Foxp3 Th2 cells contribute HDM-driven airway eosinophilia." (PMID 28507062, 2017). "A lower eosinophilia was detected in LPS-pretreated mice, along with an increase in phagocytes and regulatory cells (CD4+CD25+FOXP3+ and CD4+IL-10+), together with higher levels of IL-12 and TNFα." (PMID 32379832, 2020). "Treatment of Foxp3+ Tregs with AIP-2 (a purified product of Ancylostoma caninum), completely abrogated the protection against eosinophilia and lymphocytes infiltration of the airways, in mice." (PMID 31611876, 2019). "In comparison, anti-IL-17 antibody treatment effectively reduced neutrophilic infiltration and increased CD4+FoxP3+ cells, but it induced lung eosinophilia and did not decrease histopathology scores." (PMID 30104645, 2018). "Interestingly, this reprogramming of FoxP3+ cells had a modest impact on FoxP3 in both lung and mLNs, but reduced BAL fluid eosinophilia, a phenotype we also observed in our model (data not shown)." (PMID 32931477, 2020).
lymphoproliferative disorder (19 papers, 2008 to 2025). "Foxp3 mutations result in the scurfy (SF) mouse phenotype and a rapidly lethal lymphoproliferative syndrome." (PMID 39846845, 2025). "Foxp3 mutations result in the scurfy (SF) mouse phenotype, exhibiting a severe autoimmune phenotype with multiorgan failure and early death due to a lymphoproliferative syndrome." (PMID 39846845, 2025). "Transfer of donor CD4+CD25+ Tregs into neonatal Foxp3-deficient mice rescued the lymphoproliferative disorder in recipient mice, suggesting that Foxp3 is a critical regulator of CD4+CD25+ Treg function." (PMID 35371055, 2022). "Scurfy mice have a disabling mutation of Foxp3, which leads to a fatal lymphoproliferative disorder." (PMID 31162141, 2019). "The first evidence to suggest a role for Pak2 in Treg function followed the observation that Pak2F/F;Foxp3-Cre mice developed a severe and lethal multi-organ lymphoproliferative disorder, similar to that observed in scurfy mice possessing a mutation in the Foxp3 allele." (PMID 29213081, 2017). "Similarly, scurfy mice, which harbor mutations in the Foxp3 gene, or Foxp3-gene deficient mice suffer from a massive lymphoproliferative syndrome." (PMID 25476447, 2014). "In mice, germline deletion of Foxp3 can lead to a fatal lymphoproliferative disorder that can be restored upon adoptive transfer of Tregs from wild type mice." (PMID 32351497, 2020). "PV of the FOXP3 gene result in the fatal lymphoproliferative disorder of the scurfy mice, and the ortholog of the FOXP3 gene mutated in human causes a similar fatal disorder, namely the X-linked syndrome." (PMID 31855573, 2019). "Conditional deletion of Foxp3 in CD4+ T-cells led to a lymphoproliferative disorder mirroring scurfy phenotype." (PMID 29887862, 2018). "Deletion of Foxp3 in mice resulted in lymphoproliferative disorder identical to scurfy mice." (PMID 29887862, 2018). "In this regard, there appears to be a FOXP3 gene dosage effect, in that males with an X-linked FOXP3 mutation and a complete lack of functional FOXP3 succumb to a rapidly fatal lymphoproliferative syndrome." (PMID 18324310, 2008). "In the group of CD30+ lymphoproliferative disorders overall, CD8+ TILs significantly outnumbered FOXP3+ cells in both the edges and the centers of lesions (Wilcoxon paired-ranks test, p = 0.0014, edge; p = 0.014, center)." (PMID 31640798, 2019). "We also observed increased percentages and absolute numbers of Foxp3+ Tregs in Opnfl/flFoxp3YFP-Cre mice compared with controls, suggesting that the lymphoproliferative disorder observed in these mice was not due to reduced numbers of Treg cells." (PMID 39272810, 2024).